ITGA5 (integrin subunit alpha 5)
Diseases named in the same sentence as ITGA5 in open-access papers (continued):
Sharing a sentence is not in itself a finding about the gene and the disease.
gastric cancer (continued). "The results unveiled that integrin subunit alpha 5 was upregulated, while AKR1B10 was downregulated in gastric cancer tissues and cells." (PMID 37823316, 2023). "To further understand the upstream regulatory mechanism of ITGA5 in gastric cancer, we first used bioinformatics databases such as DIANA to predict the upstream miRNA regulated by ITGA5." (PMID 36765401, 2023). "Therefore, ITGA5 may be a potential new target in gastric cancer therapy." (PMID 36193075, 2022). "The combined genotype such as ITGA5-1160/ITGB1-1949/ITGB1 + 31804 as T/A/C carriers and COX-2-1195/IL-10-592 as G-carrier/AA, or even more specifically combined with RUNX3 + 492/TFF2-308, may thus serve as a host factor to identify the risk group of gastric cancer for an early H. pylori eradication." (PMID 25884934, 2015). "Integrin subunit alpha 5 (ITGA5) and integrin subunit beta 5 (ITGB5) may form a heterodimer in gastric cancer that positively interacts with ACTN1 to promote proliferation, invasion, and EMT." (PMID 39228892, 2024). "Moreover, similar high expression of ITGA5 was detected in five gastric cancer cells relative to GES-1 cell, among which AGS cells showed the highest ITGA5 expression; thus AGS cells were selected for further experiments." (PMID 36765401, 2023). "Moreover, they discovered that AFAP1L1 induction facilitated epithelial-mesenchymal transition (EMT) to promote the advancement of gastric cancer by activating CDC42 and ITGA5 signaling pathways, with mediation from VAV2." (PMID 37737201, 2023). "Further comparison of the clinicopathological data of 130 gastric cancer patients showed that ITGA5 expression was not significantly correlated with age, gender, and histological staging." (PMID 36193075, 2022). "Thus, ITGA5 silencing and overexpression on FAK/p-FAK, AKT/p-AKT, and PI3K/p-PI3K protein expression in two gastric cancer cell lines were evaluated by Western Blot." (PMID 36193075, 2022). "Firstly, the effect of ITGA5 gene expression on gastric cancer was only supported by bioinformatics data, lacking clinical follow-up data, while a large clinical database is needed." (PMID 36193075, 2022). "ITGA5 in gastric cancer is only predicted by bioinformatics data, without basic experimental confirmation; thus, this study further explored it role by an in-depth study using in vivo and in vitro experiments." (PMID 36193075, 2022). "ITGA5 expression was increased in gastric cancer patients with lymph node metastasis compared with no lymph node metastasis (P < 0.05)." (PMID 36193075, 2022). "Our results showed that the overexpression of the ITGA5 gene significantly increased the proliferation, invasion, and migration of MKN28 and AGS gastric cancer cells and accelerated the growth of the transplanted tumors, while opposite results were observed in the silenced group." (PMID 36193075, 2022). "ITGA5 promotes proliferation, invasion, and migration of gastric cancer cells through the activation of FAK/AKT signaling pathway, suggesting that ITGA5 may be potentially considered as a new target in gastric cancer therapy." (PMID 36193075, 2022). "However, the relationship between ITGA5 and gastric cancer is not clear, and it is only predicted by bioinformatics data." (PMID 36193075, 2022). "Subsequently, IHC and western blot were performed on adjacent normal and tumor tissues extracted from gastric cancer patients to find that Th2 cell markers such as STAT6, GATA3 and the M2 cell polarization marker CD163 were significantly increased in patients with high ITGA5 expression levels." (PMID 33711961, 2021).
lung carcinoma (15 papers, 2014 to 2025). "Our previous study showed that ITGA5 expression increased with BA treatment in lung cancer stem cells." (PMID 38963646, 2025). "As an epithelial marker, CDH1, was decreased and mesenchymal markers, CDH2, VIM, SNAI2, and ITGA5 were increased in PGC1α-silenced epithelial types of A549, H358, and Calu-1 lung cancer cells." (PMID 33917757, 2021). "ITGA5 was shown to be elevated in lung cancer tissues, and was even suggested as a possible therapeutic target." (PMID 28629363, 2017). "In lung cancer, higher expression of ITGA5 may be correlated with a shorter survival time." (PMID 29914539, 2018). "ITGA5 was significantly down-regulated after CTTPPPD administration, indicating that CTTPPPD administration can effectively inhibit lung cancer metastasis." (PMID 39275122, 2024). "The expression of some known targets of miR-31, such as ITGA5, MMP16, and RHOA, was preliminarily examined in miR-31-transfected cells and lung cancer cells." (PMID 24978700, 2014). "Moreover, all of the eight novel hypermethylation driver genes (PCDH17, IRX1, ITGA5, HSPB6, TBX5, ADCY8, GALNT13 and TCTEX1D1) were successfully validated in an independent cohort via a pyrosequencing approach, with an AUC of 0.965 for prediction of lung cancer patients." (PMID 33859751, 2021). "The remaining eight genes are newly identified methylation drivers in lung cancer, including 5 known cancer methylation driver genes in other cancer types (HSPB6, IRX1, ITGA5, PCDH17, TBX5) and 3 novel genes that had not been previously reported (ADCY8, GALNT13 and TCTEX1D1)." (PMID 33859751, 2021).
melanoma (15 papers, 2016 to 2025). A malignant, usually aggressive tumor composed of atypical, neoplastic melanocytes. "Our findings also suggest that TGF-β controls ITGA5 transcription in vemurafenib-resistant melanoma cells." (PMID 39063187, 2024). "This is the first study to report on the association between ITGB3, ITGA5, PAI1, and p21 expression and TGF-β activation in BRAFV600E vemurafenib-resistant melanoma cells and to compare parental and resistant cells in this manner." (PMID 39063187, 2024). "Overall our data propose Ust and consequently 2-O sulfated CS/DS as a regulator of adhesion via the amount and activation of FgfR1 and the expression of Itga5 in melanoma cells." (PMID 28107390, 2017). "This is the first study showing that Ust, and consequently 2-O sulfation of the low affinity receptor for FgfR CS/DS, reduces Itga5 and leads to an impaired adhesion and migration of melanoma cells." (PMID 28107390, 2017). "As a proof of concept UST knock-down in human melanoma cells also showed a reduction in ITGa5 and adhesion." (PMID 28107390, 2017). "Our results show that Ust and 2-O sulfation levels of CS/DS affect the synthesis of Itga5 and FgfR1 and, in addition, the function of α5β1 integrin which leads to impaired melanoma cell adhesion." (PMID 28107390, 2017). "ITGA5 is known to play a role in melanoma by regulating miR-148b." (PMID 34660316, 2021). "Overexpression of miR-148b in melanoma cells significantly inhibited metastasis by reducing ITGa5." (PMID 28107390, 2017). "Orso and colleagues found that inhibiting miR-214 or overexpressing miR-148b can impair melanoma metastasis, due to downregulated ALCAM and ITGA5 adhesion molecules; both of which are direct targets of miR-148b." (PMID 34943783, 2021).
pancreatic cancer (14 papers, 2018 to 2025). "This study explored migrasome-associated fibroblasts, especially TSPAN4 and ITGA5, as key regulators of pancreatic cancer metastasis, aiming to provide new ideas for therapeutic strategies targeting TME." (PMID 40443671, 2025). "Utilizing single-cell RNA sequencing and spatial transcriptomics, this study identified migrator-associated genes, including TSPAN4 and ITGA5, as critical regulators of fibroblast function in pancreatic cancer." (PMID 40443671, 2025). "ITGA5 is overexpressed in pancreatic cancer-associated stroma and activated pancreatic stellate cells (PSCs) and mediates interactions between pancreatic cancer cells (PCCs) and PSCs." (PMID 39857068, 2025). "Within the migrasome-associated genetic repertoire, TSPAN4 and ITGA5 emerge as critical effectors governing fibroblast activation dynamics and stromal communication networks, particularly within pancreatic tumor ecosystems." (PMID 40443671, 2025). "Analysis of the correlation between the pathological score of ITGA5 and the clinical information of patients with pancreatic cancer revealed that ITGA5 was associated with the pathological stage and T stage of pancreatic cancer." (PMID 39099892, 2024). "The complex distribution of TSPAN4 and ITGA5 likely with pancreatic cancer cell migration, proliferation, and ECM degradation highlights the dynamic interactions between cells that drive pancreatic cancer metastasis." (PMID 40443671, 2025). "In the present study, it was observed that fibroblasts derived from metastatic and primary pancreatic cancer tissues exhibited a notable upregulation of genes associated with migration, including TSPAN4 and ITGA5." (PMID 40443671, 2025). "Among these candidates, ITGA5 expression was substantially and negatively correlated with miR-148a-3p expression in pancreatic cancer." (PMID 39099892, 2024). "Bioinformatics analysis with 4 algorithms confirmed that ITGA5 expression was positively correlated with CAF infiltration in pancreatic cancer." (PMID 39099892, 2024). "The inhibition of ITGA5 in PSCs suppresses desmoplasia and potentiates the efficacy of chemotherapy in pancreatic cancer." (PMID 39099892, 2024). "Our findings are consistent with a previous article reporting that ITGA5 induces tumor cell proliferation and migration in pancreatic cancer through the activation of the FAK/Smad2 pathway." (PMID 36193075, 2022). "In our preliminary study, we try to investigate the feasibility of SPECT/CT imaging of pancreatic cancer by targeting ITGA5 in PSCs using 125I-labeled ITGA5 inhibitor AV3 peptide as the imaging agent." (PMID 33613761, 2021). "The overexpression of ITGA5 makes it a promising target for pancreatic cancer imaging by targeting tumor stroma, CAFs or activated PSCs." (PMID 33613761, 2021). "In our study, different from the most common strategy of targeting pancreatic cancer cells, CAFs or the activated PSCs-targeted SPECT/CT imaging of pancreatic cancer was achieved using the ITGA5-targeted molecular probe 125I-AV3." (PMID 33613761, 2021). "High expression of ITGA5 was marginally correlated with poor prognosis in pancreatic cancer (OS HR = 1.6, P = 0.12; DFS HR = 2.1, P = 0.015) and esophageal cancer (OS HR = 1.4, P = 0.37; DFS HR = 1.2, P = 0.52)." (PMID 33711961, 2021). "As a preliminary study, the feasibility of 125I-AV3 SPECT/CT imaging of pancreatic cancer by targeting ITGA5-expressing PSCs has been confirmed, but there are still some shortcomings." (PMID 33613761, 2021). "ITGA5 was overexpressed in both pancreatic cancer cells and CAFs." (PMID 39099892, 2024). "Moreover, ITGA5-EVs-148a exerted strong reconfiguration effects in inactivating CAFs and reversing tumor-promoting effects in 3D heterospheroid and xenograft pancreatic cancer models." (PMID 39099892, 2024). "Logistic regression of ITGA5 in TCGA pancreatic cancer patients." (PMID 39099892, 2024).
pancreatic cancer (continued). "ITGA5, a subunit of the fibronectin (FN) receptor, is found to be overexpressed in CAF within clinical pancreatic cancer samples." (PMID 40226936, 2025). "Targeting ITGA5 has shown promise in disrupting PCC-PSC interactions, thereby representing a potential therapeutic avenue for pancreatic cancer." (PMID 39857068, 2025). "Although previous data reported that H19 overexpression reduced ITGB3, ITGB5, and ITGA5 in bladder cancer cells and increased ITGB1 and ITGA1 in pancreatic cancer cells, the molecular mechanism by which H19 regulates integrin was not elucidated." (PMID 31426484, 2019). "Immunohistochemical analysis of tissue microarray (TMA) revealed that ITGA5 expression in pancreatic cancer tissues was higher than that in adjacent noncancerous tissues." (PMID 39099892, 2024). "Additionally, ITGA5 expression in pancreatic cancer tissues was higher than that in noncancerous tissues." (PMID 39099892, 2024). "In conclusion, our preliminary study suggests that 125I-AV3 can be used for SPECT/CT imaging of pancreatic cancer via targeting ITGA5 in PSCs, which is independent of the state of cancer cells and may have a special meaning." (PMID 33613761, 2021). "Examination of the relationship between gene expression and prognosis using the R2 platform showed that ITGB1 was significantly correlated with the prognosis of pancreatic cancer (p = 0.036), but COL4A1 (p = 0.084), COL4A2 (p = 0.121), and ITGA5 (p = 0.285) were not." (PMID 35648752, 2022). "125I-AV3 SPECT/CT imaging of pancreatic cancer-bearing nude mice showed that the radiotracer was mainly accumulated in the right tumor, and the xenografts tumor in the left lower limb has a very weak imaging, suggesting that 125I-AV3 can target the ITGA5-expressing PSCs rather than cancer cells." (PMID 33613761, 2021).
glioblastoma (13 papers, 2018 to 2024). The most malignant astrocytic tumor (WHO grade IV). "In terms of the mechanisms involved in cell adhesion, EMT transformation, and cancer invasiveness, we discovered that the ITGA5 gene, which encodes integrin alpha 5, is upregulated in glioblastoma but downregulated in lung adenocarcinoma." (PMID 38612755, 2024). "The analysis revealed upregulation of oncogenes, including FGF5, TGF-β superfamily members, and ITGA-5 in glioblastoma, which were downregulated in lung adenocarcinoma patients." (PMID 38612755, 2024). "In glioblastoma, we identified an RND1low signature of six genes (ITGA5, COL3A1, COL5A1, MET, COL1A2, LAMC1), upregulated in glioblastoma patients with low RND1, that predicts the overall survival of glioblastoma patients." (PMID 31344837, 2019). "The elevated level of miR-330-5p in glioblastoma could induce cell apoptosis via targeting ITGA5 expression in glioblastoma cells." (PMID 35111757, 2021). "In glioblastoma, miR-330-5p suppressed ITGA5 expression to impede cell proliferation and invasion." (PMID 34158077, 2021). "In consequence, targeting ITGA5 or MET genes could inhibit the invasive capacity of glioblastoma cells induced by low RND1 expression and especially the one of PVZ+ cells." (PMID 30333910, 2018). "Both mRNA and protein expression of ITGA5 are upregulated in glioblastoma, and that knockdown of the ITGA5 gene significantly inhibits the proliferation, invasion, and migration ability of glioblastoma cells, implying that ITGA5 may play a protumorigenic role in glioblastoma." (PMID 36193075, 2022). "Through analyzing patients’ clinical information and genetic profiles from online databases, TIMP1, ITGA5, FCGR2B, UPP1, ISG20, TSPAN4, and LOXL1 were identified as potential prognostic biomarkers for glioblastoma." (PMID 35778451, 2022). "We found that TIMP1, ITGA5, FCGR2B, UPP1, ISG20, TSPAN4, and LOXL1 are potential biomarkers correlated with the immune infiltration events in patients with glioblastoma." (PMID 35778451, 2022). "In addition, we used the SurvExpress analysis to further assess the prognostic value of TIMP1, ITGA5, FCGR2B, UPP1, ISG20, TSPAN4, and LOXL1 using other glioblastoma patient cohorts, including TCGA Glioblastoma and GSE4412." (PMID 35778451, 2022). "Our functional enrichment of genes in patient tumors revealed that low expression of RND1 in glioblastoma induces an overexpression of focal adhesion proteins like extracellular matrix proteins (COL1A1 and LAMB1); integrins (ITGA5 and ITGB1); actin-binding proteins (FLNA; ACTN1) and vinculin." (PMID 30333910, 2018). "Finally, based on signaling pathways activated in patients with low levels of RND1, we identified an RND1low signature of six genes (MET, LAMC1, ITGA5, COL5A1, COL3A1, COL1A2) that is an independent prognostic factor in glioblastoma." (PMID 30333910, 2018). "We used data from the GEO and TCGA databases and identified five genes (ITGA5, MMP9, PTPRN, PTX3, and STX1A) that could affect the survival rate of glioblastoma patients and that were differentially expressed between glioblastoma patients and non-tumors groups." (PMID 33767729, 2021).
hepatocellular carcinoma (13 papers, 2012 to 2026). A malignant tumor that arises from hepatocytes. "ITGA5 siRNA blocked the MSC-induced migration and invasion of hepatocellular carcinoma cells, whilst ITGA5 overexpression promoted tumor cell migration and invasion, indicating that ITGA5 expression is associated with MSC-induced tumor metastasis." (PMID 35741334, 2022). "Zhang and co - workers demonstrated that miR-148a-3p affects the progression of hepatocellular carcinoma via the ITGA5/PI3K/Akt pathway." (PMID 41114868, 2025). "For example, the expression of miR-148a-3p was found to be suppressed in activated HSC-derived sEVs and to contribute to the development of hepatoma by activating ITGA5/PI3K/Akt pathway." (PMID 39742261, 2024). "Suppression of ITGA5 can significantly inhibit stem-cell like properties in hepatocellular carcinoma." (PMID 36765401, 2023). "RNA sequencing showed an overexpression of α5 integrin (ITGA5) in the MSC-treated hepatocellular carcinoma cells." (PMID 35741334, 2022). "Intriguingly, we discovered that there is no obvious correlation between ITGA5 and FN expression level in human hepatocellular carcinomas." (PMID 25537511, 2015). "Unexpectedly, we discovered that there is no obvious correlation between ITGA5 and FN expression level in human hepatocellular carcinomas." (PMID 25537511, 2015).
bladder cancer (9 papers, 2012 to 2024). "GBX2 binding to the ITGA5 promoter promotes the viability, migration, and invasion of bladder cancer cells." (PMID 36742137, 2023). "We found an increase of ITGA5 in tumors independently of the stage (stage Ta or stage T2–4) or of the pathway of bladder cancer progression." (PMID 22724020, 2012). "Our analysis revealed that ITGB4/ITGA6 and ITGA5 were significantly downregulated with ISO treatment, suggesting that ISO may suppress cell migration and invasion of bladder cancer cells by decreasing integrin expression and activities." (PMID 38339062, 2024).